CD200 (CD200 molecule)
Diseases named in the same sentence as CD200 in open-access papers (continued):
Sharing a sentence is not in itself a finding about the gene and the disease.
lung carcinoma (16 papers, 2017 to 2026). "In the research on lung cancer, CD200+ CAFs can increase the sensitivity of epidermal growth factor receptor (EGFR) gene mutation-positive lung cancer cells to gefitinib." (PMID 40626005, 2025). "For instance, CD200‐positive CAFs significantly enhance the efficacy of the epidermal growth factor receptor (EGFR)‐tyrosine kinase inhibitor gefitinib against lung cancer cells." (PMID 41498024, 2025). "Recently, CD200 has been proposed as a marker for CAFs in lung cancer, and it has been shown that high expression of CD200 in CAFs increases their sensitivity to EGFR/TKI inhibitors, such as Gefitinib, and induces cancer cell apoptosis." (PMID 39403603, 2024). "In fact, these results paralleled clinical observations, as lung cancer patients with CD200+ CAFs experienced longer progression-free survival following gefitinib treatment relative to patients with CD200− CAFs." (PMID 38137547, 2023). "We also looked at the association of CD200 and CD200R levels with lung cancer survival using Kaplan-Meier Plotter." (PMID 33918618, 2021). "In this study, we assess both CD200 and CD200R expression in solid tumors, with a focus on lung cancer, and evaluate their association with clinicopathologic characteristics, mutation status, outcome, and programmed death-ligand 1 (PD-L1) expression." (PMID 33804482, 2021). "In conclusion, this work demonstrates the distribution and patterns of expression of the CD200/CD200R immune checkpoint in lung cancer as well as its correlation with PD-L1." (PMID 33804482, 2021). "In this study, we used quantitative immunofluorescence to characterize the CD200/CD200R immune checkpoint in lung cancer." (PMID 33804482, 2021). "Our group found CD200 to be heterogeneously expressed in lung cancer and to have correlated expression in the tumor and stromal compartments." (PMID 34771664, 2021). "We found a similar relationship of CD200 compartmental expression in lung cancer patients as well." (PMID 34771664, 2021). "CD200 is highly expressed in neuroendocrine tissues, and its expression was found by our group to be heterogeneous in the tumor and stromal compartments of lung cancer patients." (PMID 34771664, 2021). "CD200/CD200R pathway is frequently expressed in lung cancer patients." (PMID 33804482, 2021). "In this study, we used QIF to characterize the CD200/CD200R expression with a focus on lung cancer." (PMID 33804482, 2021). "This is in line with our data, showing correlations between expression of CD200 and CD200R and prognosis in lung cancer." (PMID 33918618, 2021). "We used multiplexed quantitative immunofluorescence (QIF) to measure the expression of CD200 and CD200R in a total of 455 patients from three lung cancer cohorts." (PMID 33804482, 2021). "QIF scores of CD200 and CD200R showed a continuous distribution in both the tumor and stromal compartments and were comparable between all three lung cancer cohorts." (PMID 33804482, 2021). "In lung cancer, a particular subset of CAF: CD200-positive CAF was uncovered to elevate the sensitivity of cancer cells to EGFR-tyrosine kinase inhibitor (EGFR-TKI), gefitinib, and the sensitizing potential was deprived when CD200 was knocked out." (PMID 37784082, 2023). "Immunohistochemical analysis also demonstrated that lung cancer tissue containing CD200-positive CAFs tends to be more sensitive to gefitinib compared to tissue containing CD200-negative cell." (PMID 28429795, 2017).
Alzheimer disease (15 papers, 2011 to 2024). A progressive, neurodegenerative disease characterized by loss of function and death of nerve cells in several areas of the brain leading to loss of cognitive function such as memory and language. "Moreover, the decreased expression of CD200, which occurs with ageing or in the brain of Alzheimer’s Disease (AD) patients, is associated with microglial activation." (PMID 25404894, 2014). "In other work, the IL-4 deficiency was shown to impair the expression of CD200 and CD200R in activated lymphocytes in patients with Alzheimer’s disease." (PMID 33804413, 2021). "In addition, research on Alzheimer’s disease and epilepsy in children has also found a correlation between IL-4 and CD200/CD200R expression." (PMID 37761997, 2023). "In a mouse model of Alzheimer's disease, injection of exogenous CD200 in the DG region could enhance microglia-mediated neural differentiation of neural stem cells." (PMID 37391731, 2023). "Reduced expressions of CD200 and CD200R1 have been observed in the brains of patients with multiple sclerosis and Alzheimer's disease." (PMID 37391731, 2023). "A decrease in the expression of CD200 and/or CD200R1 has been described in the brain of multiple sclerosis and Alzheimer’s disease patients." (PMID 35296683, 2022). "Alterations in the expression of CD200 and CD200R1 have been described in the brain in multiple sclerosis and Alzheimer’s disease patients." (PMID 33823877, 2021). "A decrease in CD200 and or CD200R1 expression has also been detected in the brain of Alzheimer’s disease and multiple sclerosis patients as well as in an experimental model of multiple sclerosis." (PMID 33823877, 2021). "CD200 expression is decreased in the human brain of patients with multiple sclerosis, and both CD200 and CD200R1 expression are decreased in the brain of Alzheimer’s disease patients." (PMID 22776069, 2012). "Recently, several studies have shown links between CD200/CD200R signalling and PD, Alzheimer's disease (AD) and prion diseases." (PMID 22053982, 2011). "In the present review, we scrutinize different interactions and important factors including direct cell–cell contact, intervention by the CD200 system, various receptors present on their surfaces, CXC3RI and TREM2, and chemokines and cytokines with special reference to Alzheimer’s disease (AD)." (PMID 35053818, 2022). "Moreover, the level of CD200, together with its receptor, CD200R, has been reported to be decreased in Alzheimer’s disease (AD), a neurodegenerative disease, that is characterized by ongoing chronic inflammation in the brain lesions." (PMID 27095555, 2016). "Interestingly, decreased expression of CD200 and CD200R have also been found in hippocampus and inferior temporal gyrus of patients suffering from Alzheimer's disease." (PMID 22053982, 2011).
influenza infection (15 papers, 2012 to 2024). "The role of CD200 expression in chronic viral infection has also been investigated in the influenza model, in which a host response is associated with increased Th1 cytokines and augmented activity in a macrophage (M1) population." (PMID 33562512, 2021). "Rygiel and colleagues elegantly showed that CD200 deficiency enhances pathological T cell responses during influenza infection." (PMID 30777093, 2019). "CD200−/− mice develop severe immune-mediated lung damage and morbidity following influenza infection as a result of the loss of this “dampening” of the pulmonary macrophage population." (PMID 23304058, 2012). "More recent studies with these mice have linked the CD200/R pathway to the development of bacterial pneumonia following a primary influenza infection." (PMID 23304058, 2012). "CD200R1 is expressed on alveolar macrophages and lung DC while CD200 is expressed on epithelial cells, and mice deficient in CD200 show increased mortality and delayed resolution of airway inflammation following influenza infection." (PMID 22984588, 2012). "Treatment with CD200 agonistic fusion proteins ameliorated lethal immune reactions during influenza infection, suggesting that the immunoregulatory balance of CD200 is relevant in pathological conditions." (PMID 22496920, 2012). "In the case of influenza and meningococcus, CD200−/− mice are prone to the effects of inflammation/sepsis." (PMID 23082204, 2012). "In the case of influenza and meningococcus, CD200−/− mice are prone to the effects of inflammation/sepsis, indicating that CD200R1:CD200 interaction is not likely to be involved in the regulation of cellular anti-viral mechanisms." (PMID 23082204, 2012). "Furthermore, we have previously demonstrated that an augmented T cell response to influenza infection was observed in CD200−/− animals secondary to augmented macrophage / DC responses, potentially attributable to enhanced antigen presentation." (PMID 31365119, 2019). "CD200-/- B6 mice were also found to be more susceptible to viral infections, such as influenza, where a dose causing non-fatal disease in WT mice now resulted in death." (PMID 28234914, 2017). "Similarly, this effect has been shown in influenza infection in mice, where high viral inoculum led to comparable disease between CD200-/- and WT mice opposed to significant differences between groups infected with lower viral inocula." (PMID 28005954, 2016). "Enhanced pathological T cell responses were also reported in influenza infected CD200–/– mice." (PMID 22496920, 2012). "A functional lack of CD200 results in pathology with influenza-specific NP366–374 CD8+ T cell infiltration and other pathologies in which CD4+ T cells also play a role." (PMID 33562512, 2021). "Likewise, mice lacking CD200 have an exaggerated response to influenza infection, leading to slower resolution of infection and greater lung damage." (PMID 38745652, 2024). "Interestingly, previous work has shown that mice lacking CD200 display an enhanced sensitivity to influenza infection, leading to delayed resolution of inflammation and death." (PMID 30777093, 2019). "Moreover, CD200 deletion in mice reduces lung immunopathology in influenza without significantly affecting viral clearance, suggesting its activation might be effective without resulting in severe immune suppression." (PMID 33975450, 2021).
mantle cell lymphoma (15 papers, 2016 to 2025). Mantle cell lymphoma is a rare form of malignant non-Hodgkin lymphoma affecting B lymphocytes in the lymph nodes in a region called the ``mantle zone''. "In particular, loss of CD200 was observed in mantle cell lymphomas, whose normal counterparts are early GC founder cells, suggesting that lack of CD200 may characterize GC and post-GC B cells." (PMID 30540814, 2018). "Although previous studies have confirmed the diagnostic value of CD200 in differentiating CLL from to other B-cell chronic lymphoproliferative disorders especially mantle cell lymphoma, whether CD200 has prognostic significance in CLL remains to be determined." (PMID 26910908, 2016). "While CLL and hairy cell leukemia show elevated expression of CD200, mantle cell lymphoma lacks this marker, allowing better differentiation between these different B-cell malignancies, each of which has a different prognosis." (PMID 37958359, 2023). "Since then, studies have shown that CD200 was expressed differently between CLL and mantle cell lymphoma (MCL) it is consistently expressed in CLL whereas MCL lack the expression of CD200." (PMID 37822353, 2023). "More recently differential expression of CD200 has been reported in various B-LPDs and that CD200 may improve the differentiation between chronic lymphocytic leukaemia (CLL) and mantle cell lymphoma (MCL)." (PMID 37822353, 2023). "Other combinations of markers used in conjunction with CD180, such as CD148 and CD200 or CD148 alone, have been suggested to be useful for distinguishing MZL from other malignancies such as mantle cell lymphoma (MCL)." (PMID 37460961, 2023). "CD200 was uniformly expressed on CLL leukemic cells while, in mantle cell lymphoma (MCL) cases, CD200 was only expressed in a minority of CD5 positive cells in a small subset of patients and totally absent in most cases, suggesting its value in the differential diagnosis between CLL and MCL." (PMID 26910908, 2016). "The main differential diagnosis is mantle cell lymphoma (MCL): CD5+, but classically negative for CD23 and CD200 with strong expression of CD20 and immunoglobulins." (PMID 40347842, 2025). "CD200, a glycoprotein on the surface membrane of normal B-cells, B-cell precursors, some T-cells, dendritic cells, and neurons, was first described in 2009 for being uniformly expressed in CLL, but absent in mantle cell lymphoma (MCL)." (PMID 33606850, 2021).
multiple sclerosis (15 papers, 2010 to 2024). A progressive autoimmune disorder affecting the central nervous system resulting in demyelination. "CD200 deficiency or treatment with a CD200R1-blocking antibody resulted in an enhanced pathology in an experimental model of multiple sclerosis, while the administration of a CD200R1 agonist resulted in an attenuated pathology." (PMID 33823877, 2021). "CD200 appears to limit autoimmune inflammation in animal models of multiple sclerosis and arthritis and lung injury caused by viral infection, as CD200 deficient mice were found to have a significantly increased disease severity due to hyper activation of macrophages." (PMID 22319630, 2012). "The downregulation of CD200 expression has been observed in both chronic active and inactive multiple sclerosis lesions from postmortem brains in patients." (PMID 35327492, 2022). "In the experimental autoimmune encephalomyelitis model of multiple sclerosis, we detected changes in CD200 expression in several spinal cord regions, mainly a decrease in Cd200full mRNA expression and an increase in Cd200tr mRNA levels." (PMID 35296683, 2022). "It was reported that in human multiple sclerosis (MS) patients, CD200 expression in neurons diminishes around the periphery and in the center of MS lesions; however, astrocytes in these lesions acquire CD200 expression." (PMID 23734099, 2013). "The early decreases in CD200 expression in EAE suggest that this downregulation might also occur in the initial phases of multiple sclerosis, and that this early neuronal dysfunction might facilitate the development of neuroinflammation." (PMID 28522962, 2017). "Expression of CD200, but not CD200R, was reduced in and around demyelinating plaques in multiple sclerosis (MS) allowing unrestrained microglial activation, although individual astrocytes expressing CD200 have recently been demonstrated in MS and are regarded as neuroprotective." (PMID 21152121, 2010). "The down regulation of the expression of NIRegs, CD200 and CD47, promotes microglial activity as found in demyelinating plaques from cases of multiple sclerosis." (PMID 21152121, 2010).
viral infection (10 papers, 2012 to 2024). "This appears to hold true from viral infection models that highlight the evolutionary conserved role of CD200, where its decrease triggers the innate immune response to stop the infection." (PMID 31790427, 2019). "CD200 is a widely expressed cell surface glycoprotein that inhibits excessive inflammation in autoimmunity, transplantation, and viral infections." (PMID 29721190, 2018). "Cellular CD200 restricts virus-induced immune responses in acute virus infections, and our data supports the conclusion that some viruses may exploit host CD200-CD200R interactions to establish persistence." (PMID 25654642, 2015). "Interestingly CD200–/– mice suffer severe T cell mediated immune pathology upon viral infection, implying that physiological expression of CD200 exerts immunoregulatory control over peripheral immune responses." (PMID 22496920, 2012). "Moreover, absence of CD200 increases inflammatory response to viral infection by limiting viral replication but increasing lung injury because of uncontrolled inflammation." (PMID 36591265, 2022).
basal cell carcinoma (9 papers, 2016 to 2026). A carcinoma involving the basal cells. "Recently, MMP-mediated CD200 ectodomain shedding in basal cell carcinoma was shown to regulate NK cell dysfunction and apoptosis in the microenvironment." (PMID 36738455, 2023). "In situ, CD200 underwent ectodomain shedding by metalloproteinases MMP3 and MMP11, which released biologically active soluble CD200 into the basal cell carcinoma microenvironment." (PMID 36074574, 2022). "Here we showed that the basal cell carcinoma tumor–initiating cell surface protein CD200, through ectodomain shedding, was responsible for the near absence of NK cells within the basal cell carcinoma tumor microenvironment." (PMID 36074574, 2022). "MMP3 and MMP11 have previously been shown to be involved in CD200 ectodomain shedding in basal cell carcinoma and thus may be involved in regulating the cleavage of CD200 in PDAC." (PMID 38619621, 2024). "Basal cell carcinoma (BCC)-expressed CD200 was released into the TME as soluble CD200 (sCD200)." (PMID 38283351, 2023). "This includes CD200, which has been found to be expressed on 1-2% of basal cell carcinoma cells." (PMID 27462861, 2016).
glioblastoma (9 papers, 2013 to 2025). The most malignant astrocytic tumor (WHO grade IV). "CD200 protein was found to be expressed on a variety of human brain tumors; serum CD200 concentration levels were highest for patients with glioblastoma multiforme and correlated with the expansion of MDSCs." (PMID 33804482, 2021). "In aggregate, these results support serum CD200 as a potential “liquid biopsy” platform for glioblastoma monitoring." (PMID 30682795, 2019). "In summary, our study provides data to support the use of peptide ligands that interfere with the biologic function of the CD200 immune checkpoint prior to tumor lysate vaccine administration as a novel therapy for glioblastoma." (PMID 30682795, 2019). "Although CD200 is a cell-surface glycoprotein, much of the CD200 in glioblastoma patients is released as a soluble factor." (PMID 30682795, 2019). "Of note, murine CD200AR-L priming prior to antigen presentation to the T-cells suppressed expression of inhibitory receptor, CD200R1, rendering these cells resistant to the effects of CD200 in the glioblastoma microenvironment." (PMID 30682795, 2019). "CD200 mRNA levels were measured in human brain tumors, with different expression levels being noted among the sub groups of glioblastoma, medulloblastoma and ependymoma." (PMID 25598973, 2014). "Serum CD200 concentrations were highest in patients with glioblastoma and correlated significantly with MDSC expansion." (PMID 25598973, 2014). "CD200-derived peptides were used as competitive inhibitors in a mouse model of glioblastoma immunotherapy." (PMID 25598973, 2014). "Importantly, CD200 is expressed on the surface of many types of cancer cells including glioblastoma, and can be released in a soluble form (sCD200) when cleaved by metalloproteases." (PMID 39958231, 2025). "Antigen-presenting cells and T-lymphocytes primed with this peptide suppressed their expression of the inhibitory CD200 receptor, thereby enhancing their ability to initiate immune reactions in a glioblastoma microenvironment replete with the immunosuppressive CD200 protein." (PMID 30682795, 2019). "We based this work on evidence that survival of human glioblastoma (GBM) patients is correlated with the expression of CD200/CD200R1-related genes." (PMID 30682795, 2019). "Recently published preclinical data illustrated that inhibition of the CD200/CD200R interaction can induce chemokine response, stimulate dendritic cell differentiation, enhance antigen-specific response and ultimately lead to downregulation of PD-1 receptors in glioblastoma multiforme cells." (PMID 33804482, 2021). "Interestingly, CD200 was also found to be absent on the SNB-19 glioblastoma line, while CD49f was highly expressed." (PMID 23826393, 2013). "Moreover, using the SNB-19 line of glioblastoma origin, we found CD49f present on glial fibrillary acidic protein (GFAP)-positive cells, while CD200 was not co-expressed with this glial marker, in contrast to its close correlation with the other neural markers analyzed." (PMID 23826393, 2013).